BCL2 (BCL2 apoptosis regulator)
Diseases named in the same sentence as BCL2 in open-access papers (continued):
Sharing a sentence is not in itself a finding about the gene and the disease.
liver cancer (continued). "Raloxifene inhibited the targets of STAT3, such as Bcl-2, Bcl-xl and survivin and cell viability, cell migration, and colony formation in liver cancer cells." (PMID 28430601, 2017). "With the treatment of Raloxifene for 24 hours, the expression of Bcl-2, Bcl-xl, and survivin was reduced in Hep-G2, 7721, and Huh-7 liver cancer cell-lines." (PMID 28430601, 2017). "We also examined the expression of STAT3 target genes, such as Bcl-2, Bcl-xl, and survivin in liver cancer cells by western blot." (PMID 28430601, 2017). "In this study, we observed that the vitexin suppressed liver cancer cell viability and induced apoptosis by decreasing Bcl-2 protein expression while activating Caspase-3 and its cleavage form." (PMID 27588401, 2016). "Norcantharidin potently increases ROS production, down-regulates Bcl-2, up-regulates Bax, and activates caspase-3 and -9 to induce apoptosis in liver cancer cells." (PMID 26828466, 2016). "The nuclear receptor small heterodimer partner SHP was shown recently to translocate to the mitochondria, interact with Bcl2, and induce apoptosis in liver cancer cells." (PMID 23874642, 2013). "EF24-treated liver cancer cells expressed significantly lower levels of Bcl-2 while concomitantly upregulating Bax expression, compared with control cells." (PMID 23118928, 2012). "From data obtained, treatment of liver cancer cells elicit the down-regulation in Bcl-2 and significantly up-regulated the expression of Bax." (PMID 17407577, 2007). "APS (both 100 and 200 mg/L) can suppress the activity of the Wnt/β-catenin pathway by downregulating the mRNA and protein expression of β-catenin, C-myc, and cyclin D1, as well as by inhibiting the antiapoptotic gene Bcl-2, thereby inducing apoptosis in HepG2 liver cancer cells." (PMID 40649307, 2025). "Furthermore, APS downregulated the expression of Bcl-2 while upregulating Bax and activated the caspase cascade by increasing the levels of caspase-3 and caspase-9, thereby inducing apoptosis in liver cancer cells." (PMID 40649307, 2025). "From this study we concluded that sea cucumber Ps extract can inhibit proliferation of HepG-2 cells through downregulation of VEGF and induction of apoptosis in liver cancer cells via downregulation of survivin and Bcl2 expression and upregulation of BAX, BAK and BID expression." (PMID 40550816, 2025). "Our results suggest that in the microenvironment of liver cancer, an increase in Brf1 may promote the expression of Bcl-2, thereby promoting the proliferation of liver cancer cells and inhibiting their apoptosis." (PMID 39308682, 2024). "This indicated that ITGAV may play important roles in tumorigenesis of liver cancer by activating the expression of BCL2, PXN and MAPK." (PMID 38374893, 2024). "Simultaneously, 3-formylchromone inhibits the expression of Bcl-2, Bcl-xL, Survivin, and Mcl-1 in liver cancer cells, suggesting that 3-formylchromone promotes apoptosis in liver cancer cells by suppressing the STAT3 pathway and weakening CXCL12-driven metastasis." (PMID 38920657, 2024). "Additionally, the western blot assay indicated a dose-dependent reduction in the levels of the anti-apoptotic protein Bcl2 and a marked elevation in the levels of the pro-apoptotic protein Bax upon flavokawain C treatment in liver cancer Huh-7 cells." (PMID 38460052, 2024). "It is suggested that ITGAV may play important roles in tumorigenesis of liver cancer by activating the expression of BCL2, PXN, and MAPK." (PMID 38374893, 2024).
liver cancer (continued). "In liver cancer cells, the overexpression of NOS2 and NOS3 induces a transition between apoptosis and autophagy by disrupting the Beclin 1/Vps34 association and increasing the Bcl-2/Beclin 1 interaction." (PMID 37958916, 2023). "In liver cancer cells, the apoptotic process triggered by zerumbone has been reported to involve the upregulation of pro-apoptotic Bax protein and the suppression of anti-apoptotic Bcl-2 protein expression." (PMID 35931788, 2023). "The results indicated that the Atp-MSN (ICT@FITC) NP platform could not only detect nucleolin but also inhibit cell proliferation by activating the Bax/Bcl-2/caspase-3 signalling pathway, thereby inducing liver cancer cell apoptosis in vitro and in vivo." (PMID 36843953, 2023). "In synergy with cisplatin, solanine induces apoptosis, intensifies cell cycle arrest in liver cancer cells, enhances caspase-3 and caspase-7 activity, and attenuates the expression of Bcl-2 and survivin, thereby promoting apoptosis and inhibiting cancer cell growth." (PMID 38192621, 2023). "In order to further clarify the mechanism of the ethyl acetate extract of S. emarginatum in promoting cell apoptosis, RT-PCR was used to detect the effect of the ethyl acetate extract of S. emarginatum on the expression of Bcl-2 mRNA, Bax mRNA and Caspase-3 mRNA in liver cancer HepG2 cells." (PMID 35101006, 2022). "HuH-7 liver cancer cell viability and Bcl-2 protein expression level were significantly increased." (PMID 35909586, 2022). "Our studies showed that S. emarginatum may regulated the expression of apoptosis genes such as Bcl-2 mRNA, Bax mRNA, and Caspase-3 mRNA to inhibit the proliferation of liver cancer HepG2 cells and promote cells apoptosis." (PMID 35101006, 2022). "In another study, a natural BP derivative named HPN at a very low concentration (below 1 μM, 12 h of incubation) caused apoptosis in a human liver cancer cell line (HepG2), which was associated with caspase-3 activation, changes in the BAX/Bcl2 ratio, and chromatin condensation." (PMID 36014294, 2022). "Its anti-hepatocellular mechanism may be related to affect the expression of apoptosis genes (Bax, Bcl-2 and Caspase-3mRNA) and promote the apoptosis of liver cancer cells." (PMID 35101006, 2022). "Previous studies have found that HXHJ could significantly inhibit the proliferation of liver cancer cells H22, induce the imbalance of the expression ratio of Bax and Bcl-2 proteins in the cells, and promote the apoptosis of cancer cells." (PMID 34335843, 2021). "In addition, propofol can greatly reduce the proliferation rate of liver cancer cells by regulating the mRNA division speed of liver cancer cells in patients with liver cancer, inhibiting and slowing down the expression intensity of mRNA Fas, Bcl-2, and Bax." (PMID 34323647, 2021). "Knockdown of CNPY2 in Huh7 and HepG2 human liver cancer cells resulted in significant suppression of cell survival and invasive potential, inhibition of cyclin D1, induction of p21Waf1/Cip1 and suppression of the apoptosis inhibitor Bcl2." (PMID 34298825, 2021).
liver cancer (continued). "Mechanistically, the results showed that EO suppressed BCL-2 expression, which could have been reflected in the cell proliferation and survival of HepG2 liver cancer cells." (PMID 35009072, 2021). "Two conjugates of quercetin with alkylphospholipids were demonstrated to increase the size of apoptotic cell population in liver cancer cells, to down-regulate the expression of anti-apoptotic protein Bcl-2 and also facilitate the cleavage of poly (ADP-ribose) polymerase (PARP) by caspases." (PMID 34445104, 2021). "Moreover, laminarin represses the proliferation and metastasis of liver cancer cells via a reduction in endogenous hydrogen sulfide production and effects on the pSTAT3/BCL-2 and VEGF cascades, which include MMPs, VEGF, p-AKT, and p-ERK1/2." (PMID 32182828, 2020). "Furthermore, studies in liver cancer tissues demonstrated Gli2 gene ablation reduced the expression of c-myc and Bcl-2 and elevated the p27 expression which regulates the cell cycle, reduce proliferation and inhibits the growth of liver cancer cells." (PMID 32093152, 2020). "The Bcl-2 siRNA, an antisense oligonucleotide sequence of Bcl-2, could silence the expression of Bcl-2 gene, resulting in cell apoptosis of liver cancer." (PMID 30723405, 2019). "Several molecular alterations could be associated with induction or imbalance of pro- and anti-apoptotic BCL-2 proteins in liver cancer." (PMID 31921676, 2019). "(Yin-Yang-Huo), up-regulate JNK and Bax/Bcl-2 to induce apoptosis in liver cancer cells." (PMID 26828466, 2016). "We observed enhanced expression levels of Bcl-2 and Bcl-xl genes that may lead to increased cell survival in hepatic cancer cells." (PMID 27760163, 2016). "Here we show that ILF2 might regulate Bcl-2 and cIAP1 expression in xenografted tumors and liver cancer cells, suggesting that the oncogenic function of ILF2 was at least in part by promoting the expression of Bcl-2 and cIAP1." (PMID 27556459, 2016). "XH could induce H22 cell (mouse liver cancer cell line) and Bel-7402 cell (human liver cancer cell line) apoptosis by downregulating Bcl-2 expression in tumor-bearing mice." (PMID 26170886, 2015). "Taken together, these data suggest the combination treatment of Bcl-2 inhibitor and survivin inhibition may have a great potential for liver cancer therapy." (PMID 21829603, 2011). "The result implies that apoptosis induced by zerumbone may be mediated by the Bax and Bcl-2 pathways in liver cancer cells, HepG2." (PMID 17407577, 2007). "However, the down-regulation of PPAR-γ expression promotes the overexpression of Bcl-2, inhibits Bax, and inhibits the apoptosis of liver cancer cells, indicating that PPAR-γ may promote cancer cell apoptosis." (PMID 39924893, 2025). "One study demonstrated the application of Eupolyphaga steleophaga in treating a liver cancer cell line (H22), revealing its capacity to inhibit cancer cell proliferation by inducing apoptosis, as evidenced by increased expression of caspase-3 and Bax, along with an elevated Bax/Bcl-2 protein ratio." (PMID 40005980, 2025). "Similarly, a significant elevation in BAX/BCL2 ratio to reach 9.43, 9.76, and 4.69 folds, respectively, was observed in hepatic cancer cell lines treated with doxorubicin 200 μm or sitagliptin (IC50: 89 μM; or IC35; 62.5 μM) as compared to the negative control, untreated cancer cell lines." (PMID 40786041, 2025). "Both in vitro and in vivo studies have found that 2-ME could reduce the expression of vascular endothelial growth factor (VEGF) and Bcl-2, promote cell cycle arrest and apoptosis of liver cancer cells; the overall effect: inhibition of liver cancer cell proliferation and tumor growth." (PMID 35096574, 2021). "Thus, modulation of the BCL-2 protein interplay might be a promising therapeutic strategie for liver cancer." (PMID 31921676, 2019). "Thus, high expression levels of Bcl-2 make liver cancer cells resistant to conventional treatments." (PMID 31779223, 2019).
liver cancer (continued). "Studies have shown that telekin at 2.5–10 μmol/L could significantly inhibit the cell proliferation by inducing cellular apoptosis via decreasing the expressions of Bcl-2 and Apaf-1, increasing the expression of Bax, releasing Cyt-c, and activating caspases-9 and -3 in liver cancer HepG2 cells." (PMID 31354479, 2019). "In vitro experiments with the human liver cancer cell line HepG2 showed that EVs derived from L. rhamnosus PTCC 1637 prevent liver cancer and significantly increase the apoptosis index (Bax/Bcl-2 ratio), inducing cancer cell death." (PMID 40230717, 2025). "Then, histones were extracted to detect Bcl-2 and Bax, and the results indicated that after DMF treatment, the Bcl-2/Bax ratio was decreased, indicating that DMF can induce mitochondrial apoptosis in liver cancer." (PMID 39444606, 2024). "On the other hand, a study evaluating the antiproliferative potential of pomegranate seed and peel extracts against a liver cancer cell line showed increased expression of the BAX gene and decreased expression of the BCL-2 gene." (PMID 39596317, 2024). "In liver cancer cells, MMP-9 has been found to interact with B-cell lymphoma 2 (BCL-2), an anti-apoptotic protein that prevents cell death." (PMID 38575697, 2024). "We validated the expression of apoptosis-related proteins, BAX and BCL-2, following PCMT1 knockdown in two liver cancer cell lines." (PMID 37596654, 2023). "Cryptotanshinone induced liver cancer cells apoptosis and enhanced the effect of Arsenic trioxide by downregulating phosphorylated STAT3, Bcl-2 in vitro and in vivo." (PMID 36865794, 2023). "With an increase in BAX and a decrease in BCL2, the apoptosis of cells of the VX2 liver cancer model was observed." (PMID 36354566, 2022). "The inhibition of CD133 expression diminished stemness properties, increased apoptosis via the regulation of BCL-2 and BAX, and increased chemoradiosensitivity in liver cancer stem cells." (PMID 30754694, 2019). "The expression of STAT3 target genes, Survivin, Bcl-2 and Bcl-xl, were decreased in SSMC 7721, Huh7, HEPG2 and Hep3B liver cancer cells after treatment with LY5 as examined by Western Blot." (PMID 26883202, 2016). "Gastrodin, isolated from Gastrodia elata Blume (Tian-Ma), up-regulates NF-κB, IL-2 and Bcl-2 in CD4+ T cells, and enhances cytotoxic activities of natural killer (NK) and CD8+ T cells against H22 hepatic cancer cells." (PMID 26828466, 2016). "Considering EF24’s inhibition of ERK 1/2, upregulation of activated caspase-3, and alteration of Bax/Bcl-2 and Bax/Bcl-xL ratios, we examined the therapeutic potential and molecular mechanisms of EF24 on liver cancer cells." (PMID 23118928, 2012). "Cry1 may serve as a potential therapeutic target in liver cancer, as it appears to suppress HCC progression via increased BCL2/BAX ratio to promote apoptosis." (PMID 41142939, 2025). "A combination of curcuma zedoary and kelp could inhibit liver cancer cell proliferation and metastasis by inhibiting endogenous H2S production and down-regulating the transcription activator 3 (STAT3)/BCL-2 and VEGF pathway in vitro and in vivo." (PMID 36865794, 2023). "Moreover, this application aimed at determining the outcome of inhibiting the IQGAP1 gene and, consequently, its effect upon Il-8 and its receptor family genes, caspases (3 and 9), BAX, Bcl-2, and TRAIL-induced apoptosis in the mouse liver cancer." (PMID 36276098, 2022).
liver cancer (continued). "Further studies showed that oridonin at the concentrations of 12.5–100 μM significantly induced apoptosis against liver cancer MHCC97-H cells and the effect was related to decrease of the Bcl-2/Bax ratio and increase of the activity of caspases-3, -9, and Cyt-c." (PMID 31354479, 2019). "In liver cancer cells and the tumor tissues collected from the nude mice, erianin enhanced the expression levels of Bax and Bad, and reduced the levels of Bcl-2 (which regulates MMP levels by formation of the Bcl-2/Bax heterodimer)." (PMID 31754081, 2019). "This suggests that liver cancer cell apoptosis may be induced by ADM-NMC via regulation of Bax and Bcl-2 expression." (PMID 30578377, 2019). "Consistently, we also observed an increased expression of the Bcl-2, c-Myc, cyclinD1, and MMP7 target genes in primary liver cancer tissue from DEN-treated mice (red columns); however, the DEN-stimulated expression of these genes was significantly restrained by the absence of Gab2 (green columns)." (PMID 28842424, 2017). "Research findings involving liver cancer cells (Hep-3B and SK-Hep1) and healthy liver cells (MIHA) treated with RM showed that RM induced apoptosis, as evidenced by increased expression of pro-apoptotic proteins (Bax and cleaved PARP) and decreased expression of the anti-apoptotic protein Bcl-2." (PMID 40136434, 2025). "This study was conducted in order to elucidate the role of IQGAP in mouse hepatic cancer progression and its relation with pro-apoptotic and antiapoptotic genes, such as the TNF-related apoptosis-inducing ligand (TRAIL) family genes, BAX, Bcl-2, caspase-3 and -9, IL-8, and CXC3, and other factors." (PMID 36276098, 2022). "It is interesting to note that, unlike ABT-737, ABT-199 that primarily targets BCL-2 was unable to induce efficient cell death in combination with sorafenib or regorafenib in liver cancer cells, indicating that targeting of BCL-XL, e.g., by ABT-737, might be more effective in HCC." (PMID 34312366, 2021).